ELK1 (ETS transcription factor ELK1)
Diseases named in the same sentence as ELK1 in open-access papers (continued):
Sharing a sentence is not in itself a finding about the gene and the disease.
viral infection (3 papers, 2020 to 2021). "Moreover, MER/ERK/ELK1 pathway has been shown to promote amino acid metabolism and inactivation of ELK1 results in elevated apoptosis in response to viral infection." (PMID 34026630, 2021).
clear cell renal cell carcinoma (2 papers, 2017 to 2020). "And its expression was regulated by ELK1 in renal clear cell carcinoma cells." (PMID 33066813, 2020).
cognitive deficits (2 papers, 2019 to 2025). "Since knockdown of ELK1 reduced APP amyloidogenic processing in vitro, we aimed to investigate whether knockdown of ELK1 by adeno-associated virus carrying ELK1 shRNA (AAVshELK1) could alleviate amyloid pathology and cognitive deficits in APP23/PS45 double-transgenic model mice of AD." (PMID 40307574, 2025). "Among the significantly enriched signaling pathways from KEGG analysis, oxytocin signaling pathway (PATH:04921; Cacng2, Adcy1, Kcnj4, Kcnj9, Adcy8, Pik3cd, Elk1, Adcy4, Camkk2, Cacng7, Nos3, Kcnj2) may play an important role in the sevoflurane-induced cognitive impairment." (PMID 31582589, 2019). "Since TDE-mediated inhibition of ELK1 phosphorylation could promote the ubiquitination and degradation of PS1, we sought to assess whether TDE could alleviate amyloid pathology and cognitive deficits in APP23/PS45 model mice of AD." (PMID 40307574, 2025). "Both genetic knockdown and pharmacological inhibition of ELK1 reduce APP amyloidogenic processing by promoting the SYVN1-mediated ubiquitination and degradation of PS1, thereby inhibiting Aβ generation and alleviating synaptic and cognitive impairments in a mouse model of AD." (PMID 40307574, 2025).
dementia (2 papers, 2020 to 2022). Loss of intellectual abilities interfering with an individual's social and occupational functions. "Although there is no direct evidence linking GATA2 and ELK1 with ALS, these transcription factors have been associated with dementia and neurodegeneration." (PMID 35370543, 2022).
fibrosis (2 papers, 2016 to 2025). the formation of excess fibrous connective tissue in an organ or tissue in a reparative or reactive process. "Besides, SERPINE2 was promoted by the MEK1/2-ERK1/2 pathway via the transcription factors Elk1 during the cardiac fibrosis." (PMID 39754051, 2025).
lung disease (2 papers, 2024 to 2025). "Analysis of Egr1 revealed upstream control by SRF, ELK1, and CREB, all of which are involved in activity-dependent gene expression, lung disease and response to infection." (PMID 40831503, 2025).
lymph node metastasis (2 papers, 2021 to 2023). "The results showed that ELK1 upregulation was tightly associated with the TNM stage, distant metastasis, and lymph node metastasis in patients with LUAD (p < 0.05), but not with sex, age, tumor size, smoking history, or differentiation degree (p > 0.05)." (PMID 34970415, 2021).
lymphoma (2 papers, 2019 to 2025). A malignant (clonal) proliferation of B- lymphocytes or T- lymphocytes which involves the lymph nodes, bone marrow and/or extranodal sites. "It has been demonstrated previously that the RSK family can mediate tumor invasion and metastasis through the regulation of cytoskeletal dynamics, EMT and survival signaling, and aberrant ERK/ELK1 can mediate lymphoma progression and spreading." (PMID 41221277, 2025). "In addition, we analyzed the expression profiles of ELKs in cancer tissues in the UniGene database and observed that ELK1 is a major expression type in gastrointestinal tumor, lymphoma, pancreatic tumor, primitive neuroectodermal tumor, retinoblastoma, and soft tissue/muscle tissue tumor." (PMID 31018569, 2019).
multiple myeloma (2 papers, 2022). "BCMA is a TNF receptor in the NF-κB, MAPK/ERK, p38, and JNK/Elk-1 signaling pathways that promotes cells’ growth, proliferation, and survival, as well as maintenance of an immunosuppressive tumor microenvironment in both benign and neoplastic myeloma and other lymphoproliferative malignancies." (PMID 36362214, 2022). "In addition to the demethylase activity, KDM6B upregulates the expression of the MAPK signaling pathway components including ELK1 and FOS and then mediates the growth and survival of multiple myeloma cells." (PMID 35783266, 2022).
myelogenous leukemia (2 papers, 2015 to 2024). "Overall, our results suggest that ELK1 is a potential target for treatments of myeloid leukemia." (PMID 38589882, 2024). "Given that upregulation of ELK1 will convert erythroid potential CMP into myeloid potential and knocking down of ELK1 only blocks neutrophil without affect erythroid differentiation, we believe that ELK1 could be an important target for therapies that treat myeloid leukemia." (PMID 38589882, 2024).
pancreatic adenocarcinoma (2 papers, 2021). "Besides, according to the expression of ELK1 and LGMN in pancreatic adenocarcinoma samples, all patients were distributed into two groups: the low expression group and the high expression group." (PMID 34966781, 2021).
prostate tumors (2 papers, 2014 to 2016). "However, ELK1 is expressed in the clinical spectrum of prostate tumors, and in PCa cells the activation of AR target growth genes through ELK1 was constitutive and did not entail hyper-phosphorylation or activation of immediate early genes." (PMID 27793987, 2016).
pulmonary arterial hypertension (2 papers, 2022 to 2024). Pulmonary arterial hypertension (PAH) is a group of diseases characterized by mean pulmonary artery pressure >20 mmHg and elevated pulmonary arterial resistance leading to right heart failure. "Elk1 can, in turn, positively regulate the activity of the c-fos promoter, which induces the proliferation and differentiation of pulmonary artery smooth muscle cells and promotes the process of pulmonary hypertension." (PMID 35222742, 2022).
thyroid (2 papers, 2009 to 2016). "The ERK-regulated ETS factor ELK1 was a candidate of particular interest, given the importance of BRAF-ERK signalling as a driver of thyroid tumorigenesis." (PMID 27852061, 2016). "An independent microarray data set showed the overexpression of ELK1, RUNX1 and ESRRA in the thyroid oncocytic tumours." (PMID 19536094, 2009).
urothelial carcinoma (2 papers, 2015 to 2018). A malignant neoplasm derived from the transitional epithelium of the urinary tract (urinary bladder, ureter, urethra, or renal pelvis). "We investigated the expression of ELK1 in human urothelial carcinoma cell lines, UMUC3, TCCSUP, 647V, and 5637, as well as an immortalized human normal urothelial cell line, SVHUC, by western blotting." (PMID 26342199, 2015).
urothelial neoplasm (2 papers, 2015 to 2018). A neoplasm involving a urothelium. "p-ELK1 was positive in 21 (25.3%) of 83 benign urothelial tissues (17 (20.5%) weak (1+) and 4 (4.8%) moderate (2+)) and 47 (47.5%) of 99 urothelial neoplasms (37 (37.4%) 1+ and 10 (10.1%) 2+)." (PMID 29518027, 2018).
Anxiety (1 paper, 2014). Intense feelings of nervousness, tension, or panic often arise in response to interpersonal stresses. "In contrast, blast-injury does not worsen anxiety-related behavior in Elk-1 KO mice relative to their sham counterparts." (PMID 25339878, 2014).
Ascites (1 paper, 2012). Accumulation of fluid in the peritoneal cavity (between the layers of the peritoneum that lines the abdomen). "Additional studies have shown that Elk-1 is directly phosphorylated by ERK1/2 and therefore support our findings that ascites induce phosphorylation of not only ERK1/2 but also Elk-1." (PMID 23158473, 2012).
bladder (1 paper, 2015). "Our results suggest that ELK1 plays an important role in bladder tumorigenesis and cancer progression, which is further induced by AR activation." (PMID 26342199, 2015).
brain injury (1 paper, 2014). Acute and chronic (see also brain INJURIES, CHRONIC) injuries to the brain, including the cerebral hemispheres, CEREBELLUM, and brain STEM. "We use this toolbox to study the alterations in behavior that occur following blast-induced traumatic brain injury (bTBI), and study if these behavior patterns are altered following genetic deletion of the transcription factor Ets-like kinase 1 (Elk-1)." (PMID 25339878, 2014).
cardiac hypertrophy (1 paper, 2020). "Male-specific responses in both mouse strains were enriched for ‘cardiac hypertrophy’ signaling; for example, Elk1 (transcription factor) and Hsp27." (PMID 32579111, 2020).
cervical tumor (1 paper, 2017). "Furthermore, silencing of TCONS_00026907 suppressed the growth of cervical tumors and altered the expression of ELK1, p‐ELK1, C‐fos, Cyclin D1 and Bcl‐2 in vivo." (PMID 28544557, 2017).
Cirrhosis (1 paper, 2021). A chronic disorder of the liver in which liver tissue becomes scarred and is partially replaced by regenerative nodules and fibrotic tissue resulting in loss of liver function. "Patients with decompensated cirrhosis presented a more limited alteration in TLR signalling genes, including 6 of the 17 upregulated genes observed in compensated cirrhosis, SIGIRR, IRAK1, HSPA1A, TOLLIP and ELK1, as well as downregulation of IL-1B." (PMID 34774066, 2021).
epilepsy (1 paper, 2021). A brain disorder characterized by episodes of abnormally increased neuronal discharge resulting in transient episodes of sensory or motor neurological dysfunction, or psychic dysfunction. "It should be noted, however, that the ETS expression profile is also different in epilepsy; ELF1, ELK1, ELK4, ETS1, ETS2, and ETV1 are expressed at higher levels than ELF4, ELK3, and ETV4, and there is also variability in expression among different types of epilepsy." (PMID 33671331, 2021).
Glucose intolerance (1 paper, 2023). Glucose intolerance (GI) can be defined as dysglycemia that comprises both prediabetes and diabetes. "Impairment of the biological activity of Egr-1 and Elk-1 in pancreatic β-cells leads to glucose intolerance and dysregulation of glucose homeostasis, the process that maintains glucose concentration in the blood within a narrow range." (PMID 36614256, 2023).
HCMV infection (1 paper, 2012). "Elk-1 is activated by the MAPK/ERK pathway, which is stimulated during HCMV infection." (PMID 22969428, 2012).
head and neck cancer (1 paper, 2017). A primary or metastatic malignant neoplasm affecting the head and neck. "Our analysis associated mutant PIK3CA with ELK1 and TCF4 activity in both breast and head and neck cancer, and with FOXO1 activity in BRCA but not in head and neck cancer." (PMID 28139702, 2017).
head and neck squamous cell carcinoma (1 paper, 2025). A squamous cell carcinoma that arises from any of the following anatomic sites: lip and oral cavity, nasal cavity, paranasal sinuses, pharynx, larynx, and salivary glands. "A study on Head and neck squamous cell carcinoma (HNSCC) on rodent models revealed that Protein phosphatase 6 deficiency (Ppp6c or PP6) leads to increased Ras signaling which induces ELK1 activation." (PMID 40862737, 2025). "Using NSCLC cells as well as head and neck squamous cell carcinoma, this 2011 study showed that IGFBP-3 leads to decreased ERK1/2 phosphorylation, by direct interaction with the MAPKs (in a non-IGF-dependent manner), thus limiting ELK1’s transcriptional activity." (PMID 40862737, 2025).
heart failure (1 paper, 2009). Inability of the heart to pump blood at an adequate rate to meet tissue metabolic requirements. "The Elk-1 prediction has particular relevance to the study of cardiac disease, because Elk-1 activity is modulated by both MAPK-p38 and calcineurin signaling pathways that are implicated in animal models of heart failure." (PMID 19476647, 2009). "Experimental studies in human patients have directly demonstrated changes in Elk-1 signaling during heart failure, however, highlighting the importance of discovering heart-specific targets." (PMID 19476647, 2009).
HIV-1 infection (1 paper, 2016). The type species of lentivirus and the etiologic agent of acquired immunodeficiency syndrome (AIDS). "Due to the importance of PKCθ for T-cell activation, more analysis will be needed to confirm the role of nuclear PKCθ to directly enhance viral transcription during HIV-1 infection and not only indirectly through the activation of transcription factors such as NF-κB and Elk-1." (PMID 26973648, 2016).
Hyperesthesia (1 paper, 2024). Increased sensitivity to stimulation, excluding the special senses, which may refer to various modes of cutaneous sensibility including touch and thermal sensation without pain, as well as to pain. "Then, component of this activated MAPK (c-MAPK) translocates to the nucleus resulting in elevated expression of transcription factors c-Myc, Elk-1, c-FOS and c-Jun, and caused hyperesthesia eventually." (PMID 38368171, 2024).
hyperglycaemia (1 paper, 2022). "In addition to the findings above, our present study showed that ELK1 overexpression had the same effect as the hyperglycaemia treatment." (PMID 35351142, 2022). "However, the role of ELK1 in hyperglycaemia-induced EndMT is unclear." (PMID 35351142, 2022).
Hypertension (1 paper, 2020). The presence of chronic increased pressure in the systemic arterial system. "Finally, the TF (HAND1, E4BP4, ESR1, VBP, ELK-1, POU3F2) associated with LV remodeling in hypertension were confirmed to act a crucial role in correlated heart diseases." (PMID 32664164, 2020).
intrahepatic cholangiocarcinoma (1 paper, 2014). A carcinoma that arises from the intrahepatic bile duct epithelium in any site of the intrahepatic biliary tree. "Moreover, ERBB2 signaling pathway enriched by SP1 and ELK1 has been implicated in the molecular pathogenesis of intrahepatic cholangiocarcinoma by interacting with other relevant signaling pathways, including linking to bile acid, vascular endothelial growth factor signaling." (PMID 24897108, 2014).
ischemic stroke (1 paper, 2018). A stroke disorder caused by obstruction of blood flow to the brain, due to thrombotic (local blood clot formation) or embolic (due to a blood clot or other material traveling from another site) event. "The expression levels of SRF, ELK1, SREBP1, and NRF-2 have been shown to increase in ischemic stroke models." (PMID 29856744, 2018).
left ventricular hypertrophy (1 paper, 2016). Enlargement of the LEFT VENTRICLE of the heart. "The ability of mutated HRAS to activate both ERK and ELK1 was intermediate between that of wild type and oncogenic HRAS, suggesting that this constitutional activation drives the cell proliferation in left ventricular hypertrophy." (PMID 28002430, 2016).
leiomyoma (1 paper, 2016). A well-circumscribed benign smooth muscle neoplasm characterized by the presence of spindle cells with cigar-shaped nuclei, interlacing fascicles, and a whorled pattern. "The upregulation of Elk1 induced by genistein, in this study further confirms the involvement of the MAPK/MSK/histone H3 pathway and cell proliferation transcription factors in hormonally driven leiomyoma development." (PMID 27582276, 2016).
liver cancer (1 paper, 2021). An epithelial or non-epithelial malignant neoplasm that arises from the liver. "For instance, it can reduce the activity of HBV S1p by targeting ELK1, thus inhibiting the progression of HBV-related liver cancer." (PMID 34395911, 2021).
mantle cell lymphoma (1 paper, 2025). Mantle cell lymphoma is a rare form of malignant non-Hodgkin lymphoma affecting B lymphocytes in the lymph nodes in a region called the ``mantle zone''. "A study about Carfilzomib sensitivity in mantle cell lymphoma, a hematological malignancy for which proteasome inhibitors are an approved therapy, investigated the role of Elk1 in proteasome capacity and inhibitor resistance." (PMID 40699751, 2025).
memory impairment (1 paper, 2025). "Our results demonstrate that ELK1 aberrantly increases in AD and genetic or pharmacological inhibition of ELK1 can alleviate AD-related pathology and memory impairments by enhancing the SYVN1-mediated PS1 ubiquitination and degradation, indicating that ELK1 may be a novel target for AD treatment." (PMID 40307574, 2025).
monocytic leukemia (1 paper, 2012). "For example, in response to LPS, ERK1/2-activated Elk-1, along with serum response factor (SRF), bind and activate the Egr1 promoter in THP-1 human monocytic leukemia cells." (PMID 23248776, 2012).
optic neuropathies (1 paper, 2022). "Further studies of Elk-1 and its transcriptional co-regulators, inhibitors, and gene targets could lead to new therapeutic approaches to promote CNS repair in various neurodegenerative diseases, including in optic neuropathies." (PMID 36261683, 2022).
osteoporosis (1 paper, 2018). A condition of reduced bone mass, with decreased cortical thickness and a decrease in the number and size of the trabeculae of cancellous bone (but normal chemical composition), resulting in increased fracture incidence. "Our research revealed the function of the lncRNA ODSM/miR-139-3p/ELK1 signaling pathway in osteoblasts and indicated the promising value of miR-139-3p in the preventative treatment of bone loss induced by microgravity or disuse osteoporosis." (PMID 30382082, 2018). "Our studies determined the molecular function of the lncRNA ODSM/miR-139-3p/ELK1 pathway in osteoblasts and established the potential value of miR-139-3p in preventative treatment for disuse osteoporosis." (PMID 30382082, 2018). "Therefore, this research was the first to reveal the critical role of the lncRNA ODSM/miR-139-3p/ELK1 pathway in osteoblasts, and these findings suggest the potential value of miR-139-3p in osteoporosis diagnosis and therapy." (PMID 30382082, 2018).
pancreatic ductal adenocarcinoma (1 paper, 2021). An infiltrating adenocarcinoma that arises from the epithelial cells of the pancreas. "Association of ELK1 expression with clinicopathological variables in pancreatic ductal adenocarcinoma." (PMID 34966781, 2021).
papillary thyroid carcinoma (1 paper, 2021). "To explore the role of ELK1 and LINC01638 in papillary thyroid carcinoma, we firstly looked at their expression in TPC-1, IHH-4, BCPAP and Nthy-ori 3–1." (PMID 34281460, 2021).
papilloma (1 paper, 2012). A benign epithelial neoplasm that projects above the surrounding epithelial surface and consists of villous or arborescent outgrowths of fibrovascular stroma. "As a result, compared to JWA+/+mice, only expressions of Elk1 at both mRNA (P<0.05) and protein levels were significantly down-regulated in JWAΔ2/Δ2 mouse papillomas and skin tissues." (PMID 22461904, 2012).
posttraumatic stress disorder (1 paper, 2014). "Given that posttraumatic stress disorder is a condition commonly associated with soldiers exposed to blast, a more thorough exploration of these Elk-1 dependent mechanisms of anxiogenic behavior may yield important insights for a significant clinical condition." (PMID 25339878, 2014).
pulmonary edema (1 paper, 2024). Accumulation of fluid in the lung tissues causing disturbance of the gas exchange that may lead to respiratory failure. "AAV-sh-Elk1 treatment upregulated the PaO2/FiO2 ratio and alleviated pulmonary edema, whereas AAV-sh-Elk1 and AAV-sh-Fcgr2b treatments diminished the PaO2/FiO2 ratio and exacerbated pulmonary edema." (PMID 38649840, 2024).
renal carcinoma (1 paper, 2025). A carcinoma arising from the epithelium of the renal parenchyma or the renal pelvis. "In a 2007 study employing rat models of renal carcinoma, ELK1 was investigated for a potential role in renal carcinogenicity." (PMID 40862737, 2025). "Regarding renal carcinomas, only limited data exists about the role of ELK1 in tumorigenesis and chemoresistance." (PMID 40862737, 2025).
SARS-CoV infection (1 paper, 2010). "Among those TFs deduced to be activated at 12 hrs, activation of NFκB, STAT, and Elk-1 persisted throughout the entire course of infection (i.e., 12–48 hrs), thereby suggesting their close role in regulating epithelial responses to SARS-CoV infection." (PMID 20090954, 2010).